SLC38A5 (solute carrier family 38 member 5)
Diseases named in the same sentence as SLC38A5 in open-access papers (continued):
Sharing a sentence is not in itself a finding about the gene and the disease.
cancer (28 papers, 2017 to 2025). A tumor composed of atypical neoplastic, often pleomorphic cells that invade other tissues. "In the early stages of tumorigenesis, SLC38A5 facilitates amino acid transport into cancer cells, possibly linked to its role in promoting macropinocytosis." (PMID 39973065, 2025). "As amino acids enter cancer cells via SLC38A5, H+ are exchanged out of the cell, potentially helping to maintain intracellular pH." (PMID 39973065, 2025). "MYC is a transcriptional target of β-catenin that regulates the expression of various Gln transporters crucial for the well-known “glutamine addiction” in cancer cells, including SLC38A5." (PMID 40595509, 2025). "Our findings demonstrate that both CDH17 and SLC38A5 silencing are required for enhanced cancer cell sensitivity to 5-FU, irinotecan, oxidative stress, and anoikis." (PMID 40595509, 2025). "Among transporters, SLC6A14 (ATB0,+) and SLC38A5 (SN2) cell-surface proteins provide substrates for cancer cell metabolic pathways and behave as signaling molecules." (PMID 40075600, 2025). "SLC38A5 plays two different functions in cancer cells: as amino acid transporter and as amino acid-dependent Na+/H+ exchanger." (PMID 40595509, 2025). "As such, the upregulation of SLC38A5 in cancer cells has a dual role, namely the provision of amino acids to support cell growth and proliferation and export of H+ to prevent intracellular acidification." (PMID 38339256, 2024). "Recently, SLC6A14 and SLC38A5 have been shown to be upregulated in various cancers and mediate the influx of glutamine, serine, glycine and methionine into cancer cells and are suitable for the rapid proliferation of cancer cells." (PMID 38785550, 2024). "Here, we focused on Myc because of its role as an oncogene and also because of a previous report showing that SLC38A5 (identified as SN2 in the report) is induced in cancer cells upon the ectopic expression of Myc." (PMID 38891084, 2024). "Niclosamide forces cancer cells to nutrient starvation by blocking macropinocytosis, SLC38A5-mediated amino acid entry and H+-coupled nutrient transport pathways." (PMID 36765717, 2023). "Our rationale was that when SLC38A5 is deleted, the cancer cells would find a way to upregulate any of these transporter/transporters to compensate for the loss." (PMID 37803043, 2023). "We conclude that niclosamide induces nutrient starvation in cancer cells by blocking macropinocytosis, SLC38A5 and the peptide transporter." (PMID 36765717, 2023). "Knockdown of SLC38A5 expression hindered both the migration and invasion abilities of cancer cells in the wound healing and transwell invasion assays." (PMID 37887353, 2023). "Among the amino acid transporters in the plasma membrane that are upregulated in cancer cells, SLC38A5 is unique because of the involvement of H+ efflux coupled to amino acid influx in the transport mechanism." (PMID 36765717, 2023). "We have recently discovered that the amino acid transporter SLC38A5, an amino acid-dependent Na+/H+ exchanger, activates macropinocytosis in cancer cells via amino acid-induced intracellular alkalinization." (PMID 36765717, 2023). "The direct inhibitory action of niclosamide on SLC38A5 has two important consequences with regard to amino acid nutrition in cancer cells." (PMID 36765717, 2023). "SLC38A5, an amino acid transporter, is upregulated in a variety of cancers to mediate the influx of glutamine, serine, glycine, and methionine into cancer cells." (PMID 36578780, 2022). "SLC38A5 is a glutamine co-transporter and has previously been shown to be a downstream target of c-Myc in glutamine-addicted cancers." (PMID 35257663, 2022). "SLC38A5 is a sodium-coupled transporter upregulated in multiple cancers, mediating the influx of glutamine, serine, glycine, and methionine into cancer cells." (PMID 36713586, 2022). "Despite the paucity of data on SLC38A5 in cancer, there is convincing evidence for the role of this transporter in promoting cell proliferation." (PMID 33806675, 2021).
cancer (continued). "It is possible that SLC38A5 plays a role in the transport of amino acids into cancer cells during the initial stages of carcinogenesis when the extracellular pH is not acidic." (PMID 34704597, 2021). "Since glutamine is a good substrate for SLC6A14 and SLC38A5, the Na+-coupled concentrative influx of these amino acids into cancer cells is likely to activate the heterodimeric amino acid transporter known as cystine/glutamate exchanger (SLC7A11/4F2hc)." (PMID 33806675, 2021). "As such, SLC6A14 and SLC38A5 drive cancer cell proliferation and tumor growth in specific types of solid tumors." (PMID 33806675, 2021). "SLC6A14 and SLC38A5 represent two such transporters with their unique amino acid substrate profiles and functional features that have been shown to be connected to cancer." (PMID 33806675, 2021). "If SLC38A5 does indeed provide amino acids (and other nutrients) to cancer cells, what would be the consequences in these cells due to loss of its function?" (PMID 34704597, 2021). "In contrast to SLC6A14 and SLC38A5, the other three transporters related to cancer are all amino acid exchangers, meaning that the influx of one amino acid substrate into cells is coupled to the efflux of another amino acid substrate out of the cells." (PMID 33806675, 2021). "The pH dependence of SLC38A5 deserves some discussion with regard to the relevance of this transporter to cancer." (PMID 34704597, 2021). "Among these five amino acid transporters that have received attention with regard to their biological relevance to cancer, SLC6A14 and SLC38A5 stand out in terms of their functional features that are ideal for the promotion of cancer." (PMID 33806675, 2021). "As cancer cells generate massive amounts of lactic acid, there is an absolute need for these cells to prevent intracellular acidification, and SLC38A5 contributes to this process." (PMID 33806675, 2021). "SLC6A14 and SLC38A5 are the two transporters that are upregulated in a variety of cancers to mediate the influx of glutamine, serine, glycine, and methionine into cancer cells." (PMID 33806675, 2021). "The Cancer Genome Atlas (TCGA) database provides evidence for the upregulation of SLC38A5 at least in pancreatic cancer and an inverse correlation between the expression levels of the transporter and survival in patients with this cancer." (PMID 33806675, 2021). "Here we have unraveled another interesting and important relationship between SLC38A5 and cancer cell biology." (PMID 34704597, 2021). "Thus, SLC38A5 prevents intracellular acidification resulting from the excessive generation of lactic acid in cancer cells by mediating the transfer of amino acids and Na+ into cells, leading to the removal of intracellular H+." (PMID 40075600, 2025). "An increased expression of SLC38A5 in cancer tissues compared to normal mucosa was detected." (PMID 40595509, 2025). "In addition to mediating the uptake of amino acids, SLC38A5 also promotes macropinocytosis, a special form of nutrient uptake in cancer cells." (PMID 38539825, 2024). "Recent studies have shown that the amino acid transporter SLC38A5 is upregulated in some cancers." (PMID 38339256, 2024). "Therefore, we aimed to study the effect of glutamine transported by SLC38A5 in gemcitabine-resistant cancer cells." (PMID 37887353, 2023). "Under the catalysis of glutamine-specific glutaminase (GLS), glutamine is taken into cells via the glutamine transporter protein ASCT2 (also known as SLC38A5) and SN2 and is catabolized to glutamate; the increased expression of this gene is essential for the development of cancer." (PMID 36568190, 2022). "The amino acid-dependent Na+/H+ exchange activity of SLC38A5 promotes macropinocytosis, which may contribute significantly to amino acid nutrition in cancer cells." (PMID 34704597, 2021). "Relatively much less is known on the expression and function of SLC38A5 in cancer." (PMID 33806675, 2021).
cancer (continued). "SLC38A5 (also known as SN2) should also be added to this elite list prompted by the findings that it is a target for the c-Myc oncogene, but relatively much less is known on this transporter in cancer compared to the other four transporters." (PMID 33806675, 2021). "Interestingly, similar to SLC6A14, the expression of SLC38A5 is also under the control of the Wnt signaling pathway, thus suggesting a probable connection between this transporter and cancer." (PMID 33806675, 2021). "When amino acids enter cancer cells via SLC38A5, it promotes the efflux of H+, which might contribute to the maintenance of intracellular pH." (PMID 34704597, 2021). "The SLC38A5 transporter in particular promotes the uptake of nutrients for glutaminolysis and the serine-glycine-one-carbon pathway, which promotes the proliferation, survival, and growth of cancer cells." (PMID 34639154, 2021). "SLC6A14 and SLC38A5 are cell-surface proteins that support amino acid nutrition in cancer cells." (PMID 33806675, 2021). "Thus, during the initial stages of carcinogenesis, SLC38A5 plays a role in the transport of amino acids to cancer cells, which may be related to the promotion of macropinocytosis." (PMID 39973065, 2025). "Since the selenoenzyme GPX4 is a critical component of the antioxidant machinery in TNBC cells, the possible involvement of SLC38A5 in the delivery of selenium into cancer cells in the form of Se-Met could represent a novel function of the transporter in promoting cancer growth." (PMID 38539825, 2024). "Since the selenoenzyme GPX4 is a critical component of the antioxidant machinery in TNBC cells, the possible involvement of SLC38A5 in the delivery of selenium to cancer cells in the form of Se-Met may represent a novel function of the transporter in promoting cancer growth." (PMID 38785550, 2024). "Therefore, SLC38A5, as not only the provider of amino acids but also as an activator of macropinocytosis, assumes a unique place among the amino acid transporters that are known to be upregulated in cancer." (PMID 35204736, 2022). "Various primary transporters, including B0AT1(SLC6A19), LAT1 (SLC7A5), SNAT5 (SLC38A5), and ASCT2 (SLC1A5), play significant roles in glutamine uptake by cancer cells." (PMID 40223274, 2025). "SLC38A5 is up-regulated in TNBC cell lines and promotes macropinocytosis, an endocytic process by which cancer cells uptake large amounts of extracellular fluid and its components." (PMID 39973065, 2025). "However, it remains unclear whether SLC38A5 plays a significant role in cancer metastasis." (PMID 37887353, 2023). "From a cancer perspective, SLC38A5 induces a sub-population of α-cells to induce PNET11 and recently, we have shown the relevance of SLC38A5 in inducing macropinocytosis in TNBC12." (PMID 37803043, 2023). "In a similar manner, it is also possible that SLC38A5 and the H+-coupled lactate transporter MCT1 (SLC16A1) are functionally coupled in cancer cells via H+." (PMID 33806675, 2021). "Cancer cells upregulate multiple amino acid transporters as a means to increase the influx of amino acids from circulation; this includes the transporters SLC7A5 (LAT1), SLC1A5 (ASCT2), SLC6A14 (ATB0,+), SLC7A11 (x-c), SLC38A5 (SNAT5) and SLC43A2." (PMID 36765717, 2023). "Not much work has been conducted on SLC38A5 and its relevance to cancer except for two papers that talk about its role in PNET, and its relevance to macropinocytosis in triple-negative breast cancer." (PMID 37803043, 2023). "Moreover, given that SLC38A5-based glutamine transport leads to proton flux and intracellular alkanization, overexpression of SLC38A5 has also been hypothesized to be a strategy for pH regulation in cancer cells that regularly experience intracellular acidification due to high glycolytic flux." (PMID 35257663, 2022).
cancer (continued). "Since a slightly alkaline pH inside the cells promotes DNA synthesis and supports cell proliferation, SLC38A5 (and maybe also SLC38A3 too) is upregulated in certain cancers to support amino acid nutrition, as well as to maintain intracellular pH at a slightly alkaline side." (PMID 36765717, 2023). "Unlike other amino acid transporters, SLC38A5 mainly transports glutamine into the cancer cells." (PMID 37887353, 2023).
tumor (19 papers, 2015 to 2025). "To understand how SLC38A5 loss attenuates tumor growth in athymic nude mice, we wanted to check the amino acid profile between the control and KO tumors." (PMID 37803043, 2023). "This could provide us clues to understand tumor attenuation mechanisms associated with SLC38A5 knockout." (PMID 37803043, 2023). "As the tumor microenvironment becomes acidic, the amino acid transport by SLC38A5 can reverse, leading to the efflux of amino acids and Na+ in exchange for extracellular H+." (PMID 39973065, 2025). "Selenium is obligatory for the antioxidant function in mammalian cells and, therefore, the SLC38A5-mediated delivery of selenium ought to be an essential feature of this transporter as a tumor promoter in TNBC." (PMID 38539825, 2024). "Using CRISPR/Cas9-mediated knockout of SLC38A5, we show its tumor promoting role in an in vitro cell line model as well as in a subcutaneous xenograft mouse model." (PMID 37803043, 2023). "In order to better understand the tumor promoting role of SLC38A5, CRISPR/Cas9 knockout was conducted." (PMID 37803043, 2023). "Using CRISPR/Cas9-mediated knockdown, we demonstrate the tumor promoting role of SLC38A5 in both cell lines and in athymic nude mice." (PMID 37803043, 2023). "These literature evidences, substantiated with our own findings demonstrate SLC38A5 as a tumor promoter." (PMID 37803043, 2023). "Since many of these amino acids are SLC38A5 substrates and since their levels were reduced in the KO tumors, it makes sense as to why mTORC1 pathway was inhibited in the KO tumor samples." (PMID 37803043, 2023). "Inhibition of SLC38A5 increased lipid ROS level and led to ferroptosis, suppressing tumor growth and metastasis in vivo." (PMID 37887353, 2023). "Therefore, we hypothesized that SLC38A5 loss would significantly impact the levels of these amino acids in the KO tumors, leading to mTORC1 inactivation, ultimately leading to an overall reduction in tumor growth." (PMID 37803043, 2023). "One gene related to solute transport that we also see upregulated in the metastatic group is SLC38A5, which alkalinizes tumor cells and promotes growth; it is also a transcriptional target for the oncogene c-Myc." (PMID 32850445, 2020). "While the exact transporters involved in serine uptake within tumours remain incompletely defined, members of the solute carrier (SLC) superfamily, such as SLC1A4 (ASCT1), SLC1A5 (ASCT2), SLC7A10, SLC38A2, SLC38A4 and SLC38A5, have been implicated." (PMID 40660426, 2025). "Therefore, the ability of SLC38A5 to potentiate Nrf2 signaling with a resultant increase in SLC7A11 expression is important, underscoring the tumor-promoter role of SLC38A5." (PMID 38539825, 2024). "We have recently shown that SLC38A5 functions as a tumor promoter in TNBC." (PMID 38539825, 2024). "Likewise, in the in vivo mouse xenograft study, the group of mice injected with HPAF-II/SLC38A5/CRISPR KO cells had a significant reduction in tumor volume when compared to the group injected with HPAF-II/NTC cells." (PMID 37803043, 2023). "Similarly, we observed that knockdown of SLC38A5 restored gemcitabine sensitivity by hindering tumor growth and metastasis in the orthotopic mouse model." (PMID 37887353, 2023). "Taken together, the data clearly demonstrate the tumor-promoting role of SLC38A5." (PMID 37803043, 2023).
tumor (continued). "Overall, these data did indicate that SLC38A5 might be a tumor promoter, further alluding that a more efficient knockdown/knockout of SLC38A5 would enable us to better understand its role in tumor promotion in PDAC." (PMID 37803043, 2023). "Moreover, inhibition of SLC38A5 hindered tumor growth in both the gemcitabine-sensitive and gemcitabine-resistant groups." (PMID 37887353, 2023). "Additionally, we observed that SLC38A5 expression increased with a corresponding increase in the tumor grade." (PMID 37803043, 2023). "SLC38A5 could carry out a similar function in solid tumors at advanced stages because of the acidic tumor microenvironment." (PMID 34704597, 2021). "Furthermore, it was interesting to observe that five out of the eight amino acids substrates that were downregulated are also mTORC1 activators, suggesting mTORC1 inhibition as one of the possible mechanisms of tumor attenuation in response to SLC38A5 knockout." (PMID 37803043, 2023). "Having identified mTORC1 signaling pathway inactivation as a mechanism for tumor attenuation in response to SLC38A5 knockout, we were curious to identify additional pathways or targets that could function either independently or in conjunction with mTORC1 pathway, to reduce tumor growth in PDAC." (PMID 37803043, 2023). "The results showed that PSAT1 and PSPH were consistently upregulated in tumour tissues in five GEO datasets, while PHGDH, SLC1A4 and SLC38A5 were upregulated in four datasets." (PMID 40660426, 2025). "Upregulation of SLC38A5, an amino acid transporter and a positive regulator of macropinocytosis, has been observed in TNBC tumours." (PMID 39420093, 2024). "By analyzing TCGA data in the GEPIA database, we found that the expression levels of multiple SLC38A family members (including SLC38A2, SLC38A4, SLC38A5, SLC38A6, SLC38A7, SLC38A8, SLC38A9, and SLC38A10) were significantly upregulated in GC tumor tissues." (PMID 36918802, 2023). "Expression levels of SLC38A5, EMT markers, and ferroptosis markers were reduced in the tumor and livers of the knockdown group in accordance with the in vitro results; the treatment of Ferrostatin-1, however, negated the effect of the knockdown." (PMID 37887353, 2023). "Taken together, we show that SLC38A5 is significantly upregulated in PDAC and its knockout significantly attenuates tumor growth." (PMID 37803043, 2023). "There are several glutamine exchangers (ASCTs and Na+-coupled neutral amino acid transporters (SNATs)) that are often overexpressed by tumor cells (e.g., ASCT2 — SLC1A5; SNAT1 — SLC38A1, SNAT2 — SLC38A, and SNAT5 — SLC38A5)." (PMID 35029792, 2021). "Metabolic reprogramming of tumor cells in the TME promotes the expression of L-glutamine transporters ASCT2(SLC1A5) and SN2(SLC38A5), alongside glutamic acid–metabolizing enzymes (e.g., glutaminase [GLS]), glutamine synthetase, and aminotransferases, thereby increasing L-glutamine intake." (PMID 39227970, 2024). "Thus, Se-Met enables the functional coupling between SLC38A5 and SLC7A11 and this crosstalk between the two transporters forms an integral part of the antioxidant machinery in tumor cells." (PMID 38539825, 2024).